CRIPTO3 (cripto, EGF-CFC family member 3)
Description:
Could play a role in the determination of the epiblastic cells that subsequently give rise to the mesoderm. Activates the Nodal-dependent signaling pathway.
Synonyms: CRIPTO-3; TDGF1P3; TDGF2; TDGF3; CR-3; TDGF1
Tractability: Antibody: UniProt places it where antibodies can reach, with high confidence; its Gene Ontology location is reachable by antibodies, with high confidence.
Gene: Protein-coding gene on chromosome X (110,520,312 to 110,523,021, forward strand). Ensembl gene ENSG00000225366.
Subcellular location: Cell membrane
Subcellular location (Human Protein Atlas): Vesicles
Pathways (Reactome):
Developmental Biology: Regulation of signaling by NODAL; Signaling by NODAL
Gene Ontology:
Molecular function: activin receptor binding; growth factor activity; nodal binding
Biological process: signal transduction; anterior/posterior pattern specification; blood vessel development; determination of left/right symmetry; heart development; nodal signaling pathway
Cellular component: plasma membrane; cell surface; extracellular region
Homologues: Orthologues: macaque TDGF1 (92% identical), chimpanzee CRIPTO3 (89% identical), rat Cripto (65% identical), mouse Cripto (63% identical). Paralogues in human: CRIPTO (97% identical), CFC1 (27% identical), CFC1B (26% identical), EGFL7 (22% identical), EGFL8 (19% identical).
Diseases named in the same sentence as CRIPTO3 in open-access papers:
CRIPTO3 is named in the same sentence as 104 diseases in open-access papers, as found by Europe PMC text mining. Sharing a sentence is not in itself a finding about the gene and the disease. The quoted sentences say what the papers report.
breast carcinoma (3 papers, 2010 to 2024). "For instance, the oncogenic CRIPTO3 pseudogene is expressed in colon, breast and lung cancers, the human homologue of vaccinia virus H1 phosphotase gene clone 5 (hVH-5) pseudogene is expressed in breast cancer cell lines, and the rac1 pseudogene is expressed in brain tumors." (PMID 20625391, 2010).
germ cell tumor (2 papers, 2012 to 2021). A benign or malignant, gonadal or extragonadal neoplasm that originates from germ cells. "Although CRIPTO expressed from the TDGF1 gene is predominant in ESCs and germ cell tumors, a highly homologous pseudogene, TDGF1P3, is expressed and likely produces functional protein (CRIPTO-3; CR-3; TDGF3) in various cancer types, including colon, breast and lung." (PMID 34576327, 2021).
triple-negative breast carcinoma (1 paper, 2020). An invasive breast carcinoma which is negative for expression of estrogen receptor (ER), progesterone receptor (PR), and human epidermal growth factor receptor 2 (HER2). "Pretreatment with a sulforaphane compound had in vivo tumor inhibitory effects, which were mediated through reduced Cripto and other stem cell markers, ALDH1A1, Nanog, and homologue CRIPTO-3 expression in triple negative breast cancer." (PMID 32517087, 2020).
cancer (13 papers, 2012 to 2025). A tumor composed of atypical neoplastic, often pleomorphic cells that invade other tissues. "Further, SFN inhibits cell proliferation and mammosphere formation of CSCs in TNBC by decreasing the expression of cancer-specific CR1 and CRIPTO-3/TDGF1P3 genes." (PMID 40013196, 2025). "TDGF3, also known as TDGF1P3 or CRIPTO3, is expressed in cancer." (PMID 33299869, 2020).
CRIPTO3 also shares sentences with these, for which no sentence is quoted: infection (60 papers); tumor (39); Alzheimer disease (8); bacterial infection (6); Cognitive impairment (6); lupus (6); Candida infections (5); HIV-1 infection (5); leukocyte adhesion deficiency (4); cognitive decline (3); frontotemporal dementia (3); fungal infection (3); glaucoma (3); gonococcal infection (3); Parkinson disease (3); Sepsis (3); Stroke (3); viral infection (3); amyotrophic lateral sclerosis (2); autoimmune disease (2); brain tumors (2); candidiasis (2); co-infection (2); Cough (2); COVID-19 (2); E. coli infection (2); Francisella tularensis Infection (2); injury (2); ischemic stroke (2); leprosy (2).
A further 70 diseases each share a sentence with CRIPTO3 in 2 papers or fewer.